RAD51 (RAD51 recombinase)
Diseases named in the same sentence as RAD51 in open-access papers (continued):
Sharing a sentence is not in itself a finding about the gene and the disease.
esophageal cancer (10 papers, 2011 to 2023). A primary or metastatic malignant neoplasm involving the esophagus. "Overexpression of RAD51 was previously shown to reverse cisplatin-induced DNA damage and chemosensitivity in esophageal cancer, which means that the success of chemotherapy was reduced in RAD51+ patients." (PMID 36837562, 2023). "While RAD51 displays a protective role, scholars have found that RAD51 is overexpressed in several tumor types, including breast, pancreatic, head and neck, prostate, non-small cell lung, and esophageal cancers." (PMID 32190537, 2020). "To demonstrate that it is the downregulation of RAD51 that is responsible for this effect of berberine, we next depleted RAD51 in esophageal cancer cells by RNAi and tested their radiosensitivity." (PMID 21858113, 2011). "Berberine can effectively downregulate RAD51 in conferring radiosensitivity on esophageal cancer cells." (PMID 21858113, 2011). "Together, these results showed that berberine was able to downregulate the expression of RAD51 in esophageal cancer cells at transcription level." (PMID 21858113, 2011). "We next cloned the promoter and the 5′end region of RAD51 (from −1693 to +487 bp) into a luciferase reporter plasmid, pGL3-basic vector, transfected them into esophageal cancer cells, and tested the RAD51 promoter activity in response to berberine treatment." (PMID 21858113, 2011). "As expected, the depletion of RAD51 led to a significant reduction in the clonogenic cell survival for both esophageal cancer cell lines." (PMID 21858113, 2011). "RAD51 is overexpressed in many cancer cell lines and primary tumors, including breast, pancreatic, prostate, non-small cell lung, and esophageal cancers." (PMID 37798649, 2023). "In this study, high expression of Rad51 was associated with lymph node metastases in cases of esophageal cancer in which the patients had not undergone NACRT." (PMID 24065387, 2014). "Interestingly, berberine treatment also down-regulated RAD51 in three additional esophageal cancer cell lines (KYSE410, EC109, and TE-1), as in KYSE30 and KYSE450 cells (data not shown), suggesting that the berberine may render radiosensitizing effect to a broad array of esophageal cancer cells." (PMID 21858113, 2011). "Second, we did not perform the positive control for IHC staining of RAD51 in this study; instead, we used an image as a positive reference from a previous study of esophageal cancer." (PMID 37798649, 2023). "Recently, overexpression of Rad51 was found as a negative predictive marker for neoadjuvant therapy using cisplatin/5-FU to treat esophageal cancers again arguing that high Rad51 levels may confer tumor cell resistance towards DNA damaging drugs." (PMID 25909291, 2015). "We show that transgenic as well as chemical suppression of AP nucleases inhibits RAD51 expression in MM as well as esophageal cancer (not shown) cells, whereas transgenic upregulation of APEX1 as well as APEX2 induces RAD51 expression." (PMID 30301882, 2018).
pancreatic adenocarcinoma (10 papers, 2006 to 2025). "The expression level of RAD51, analyzed using GEPIA, was higher in pancreatic adenocarcinoma tissues compared to normal pancreatic tissues." (PMID 36262061, 2023). "Capan‐1 cells derived from a pancreatic adenocarcinoma carry a C‐terminal BRCA2 truncation, which impairs RAD51 nuclear localisation." (PMID 31273933, 2019). "RAD51's pan‐cancer disease‐specific survival (DSS) analysis predicted poor prognosis in nine cancers: OSCC, MESO, LGG, KIRP, LUAD, pancreatic adenocarcinoma (PAAD), HNSC, skin cutaneous melanoma (SKCM) and BLCA, with statistical significance (p < 0.05)." (PMID 41350246, 2025).
bladder cancer (9 papers, 2013 to 2025). "As an example, an association between a miRNA binding site SNP within the DNA repair gene RAD51 with bladder cancer risk and radiotherapy outcomes has been reported." (PMID 26735576, 2016). "Rs7180135 is located within the miR-197 binding site in the 3′UTR of RAD51, and the minor allele was reported to be associated with an improved cancer-specific survival of bladder cancer patients." (PMID 24146953, 2013). "We also demonstrated that the RAD51-focus formation assay can be used as a marker for hyperthermia-mediated induction of HR-deficiency in bladder cancer specimens, and that the RAD51-focus response could potentially be a biomarker for hyperthermia-efficacy." (PMID 30550547, 2018). "We found that BRCA2 and RAD51 were significantly upregulated in bladder cancer samples in the TCGA/BLCA RNA-Seq data, and that the expression of BRCA2 significantly correlated with that of RAD51 (Spearman R = 0.63; and p-value < 0.001)." (PMID 37355516, 2023). "The combination treatment decreased Rad51 expression in bladder cancer cells, suggesting that exposure to the combination treatment decreased homologous recombination activity and the accumulation of DNA damage." (PMID 33986399, 2021). "The number and appearance of RAD51-foci altered substantially upon hyperthermia in both bladder cancer cell lines, indicating that RAD51-focus formation could be a suitable biomarker for determining the effectivity of hyperthermia in bladder tumors." (PMID 30550547, 2018). "The cytochrome C release assay (apoptosis) and the RAD51 focus formation assay (DNA repair) were first established in the bladder cancer cell lines RT112 and T24 as measurements for hyperthermia efficiency, and subsequently tested in freshly obtained bladder tumors (n = 59)." (PMID 30550547, 2018). "Indeed, striking ER-stress in tumor may explain upregulation of BRCA2 and RAD51 expression in bladder cancer cells." (PMID 37355516, 2023). "More specific to our research, a report has shown that mocetinostat can enhance the radiosensitivity of bladder cancer cells, which appeared to be mediated through reducing the protein levels of MRE11, RAD51, and NBS1 involved in DSB repair." (PMID 39682293, 2024). "The expression levels of EME1, RAD51, RAD51AP1, and RAD54L genes were significantly higher in high grade bladder cancer and invasive bladder cancer (p < 0.05) than in low grade bladder cancer and superficial bladder cancer." (PMID 35559013, 2022). "Moreover, in 413 bladder cancer samples (data derived from TCGA), a significantly higher expression level of four genes, RAD21, RAD51, BARD1, and ERBB2, was observed in ERBB-low as compared to ERBB-high tumours." (PMID 39080120, 2024).
hepatocellular carcinoma (9 papers, 2010 to 2023). A malignant tumor that arises from hepatocytes. "In turn, the functional RAD51 rs12593359 T>G was proposed to affect miR-129-3p binding, and the GG genotype correlated with lower mRNA levels in lymphoblastoid cell lines and fibroblasts, as well as with better OS in hepatocellular carcinoma." (PMID 37894339, 2023). "Furthermore, in additional cancers such as oral squamous cell carcinoma and hepatocellular carcinoma, palbociclib significantly inhibits cellular growth, accelerates senescence and apoptosis, and suppresses RAD51 foci formation." (PMID 34932500, 2022). "Therefore, more research into the roles and activities of Rad51 in hepatocellular carcinoma (HCC) is required." (PMID 34115569, 2021). "We identified 4 hub genes, namely, LAMA4, POLA2, RAD51, and TYMS, which were used as the final variables, and found that AdaBoostClassifie was the best algorithm for the classification and diagnosis model of hepatocellular carcinoma." (PMID 37051625, 2023). "The hepatocellular carcinoma (HCC) line HuH-7 was defective in FANCD2 monoubiquitination and FANCD2 nuclear focus formation but proficient in RAD51 focus formation." (PMID 20509860, 2010).
lymphoma (9 papers, 2019 to 2025). A malignant (clonal) proliferation of B- lymphocytes or T- lymphocytes which involves the lymph nodes, bone marrow and/or extranodal sites. "For example, mutations affecting the loading of RAD51 show a strong predisposition to lymphomas, whereas mutation of Brca1, which affects resection, induces a larger type of tumor." (PMID 33923105, 2021). "Furthermore, the therapeutic modulation of RAD51 activity-especially in combination with PARP inhibitors offers promising avenues for treating retrovirus-associated malignancies such as adult T-cell leukemia/lymphoma." (PMID 41420694, 2025). "Together, these data suggest that the BRCA1-delta11q isoform of BRCA1, which maintains its RAD51 loading activity, provides further evidence that inactivation of BRCA1-mediated RAD51 loading fuels lymphoma development in mice." (PMID 33923105, 2021). "In contrast, the Tr53bp1 and Brca1 double knockout mice that are proficient in DNA end resection but defective for RAD51 loading have reduced lifespan, and the mice that survive to adulthood develop lymphomas." (PMID 33923105, 2021). "The result showed that curcumin induced DNA damage and triggered caspase-3-dependent apoptosis by regulating Rad51-dependent homologous recombination, making lymphoma cells sensitive to various DNA damage reagents." (PMID 32083122, 2019). "In addition, targeting RAD51 was reported to enhance chemosensitivity of adult T-cell leukemia-lymphoma cells by reducing DNA double-strand break repair." (PMID 35359409, 2022). "In addition to lymphoma, we also verified the synergistic effect of RAD51 inhibitors with cisplatin on solid tumor cells." (PMID 35646698, 2022). "In addition, the depletion of Rad51 recombinase induces spontaneous DNA damage and prolonged G2 phase arrest in chicken lymphoma-B DT40 cells." (PMID 34208028, 2021).
nasopharyngeal carcinoma (9 papers, 2014 to 2026). A carcinoma arising from the nasopharyngeal epithelium. "Subsequent investigations have unveiled that circCDYL2 actively enhances RAD51’s translation, thus promoting HR repair and contributing to radiotherapy resistance in nasopharyngeal carcinoma." (PMID 38654320, 2024). "Immunofluorescence assays have demonstrated that circCDYL2 promotes the formation of RAD51 foci, a crucial protein within the HR pathway, in nasopharyngeal carcinoma cells following radiation treatment." (PMID 38654320, 2024). "To confirm that RAD51 is the mediator of radiotherapy resistance induced by circCDYL2, we simultaneously overexpressed circCDYL2 and knocked down RAD51 in nasopharyngeal carcinoma cells." (PMID 38654320, 2024). "In summary, these findings collectively suggest that circCDYL2 enhances RAD51 translation, thereby promoting homologous recombination repair in nasopharyngeal carcinoma cells following radiotherapy, ultimately leading to radiotherapy resistance." (PMID 38654320, 2024). "Further investigation revealed that circCDYL2 recruits EIF3D to promote RAD51 translation initiation, thereby fostering homologous recombination repair and contributing to radiation resistance in nasopharyngeal carcinoma." (PMID 38654320, 2024). "Comet assays further confirmed that the knockdown of RAD51 could impede the DNA damage repair induced by circCDYL2 overexpression, whereas overexpression of RAD51 in circCDYL2-knockdown nasopharyngeal carcinoma cells enhanced DNA damage repair." (PMID 38654320, 2024). "Targeting circCDYL2 and RAD51 could represent promising therapeutic strategies for sensitizing nasopharyngeal carcinoma to radiotherapy." (PMID 38654320, 2024). "Conversely, the overexpression of RAD51 in circCDYL2-knockdown nasopharyngeal carcinoma cells could counteract the reduction in HR repair efficiency caused by circCDYL2 knockdown." (PMID 38654320, 2024). "Clonogenic assays also unveiled that the knockdown of RAD51 partially reversed the increased clonogenic capacity of cells observed after circCDYL2 overexpression, whereas the expression of RAD51 enhanced the survival of nasopharyngeal carcinoma cells following circCDYL2 knockdown." (PMID 38654320, 2024). "Polysome profiling assays further demonstrated that overexpressing or knocking down EIF3D in nasopharyngeal carcinoma cells could partially counteract circCDYL2’s influence on RAD51 translation." (PMID 38654320, 2024). "Similarly, our findings were corroborated in archived clinical nasopharyngeal carcinoma tissue samples, where RAD51 exhibited high expression levels." (PMID 38654320, 2024). "Additionally, in gene expression profile data obtained from four sets of clinical nasopharyngeal carcinoma tissue samples downloaded from the GEO (Gene Expression Omnibus) database, RAD51 was markedly upregulated in nasopharyngeal carcinoma tissues compared to control tissues." (PMID 38654320, 2024). "A similar study in a nasopharyngeal carcinoma (NPC) (CNE2RR) cell line induced the expression of NFBD1, BRCA1, BRCA2, RPA1, and RAD51 proteins widely associated with HR and radioresistance." (PMID 34900673, 2021). "The recently-published results of the treatment of xenografts of nasopharyngeal carcinomas with abexinostat showed not only enhanced cytotoxic effects of irradiation (1 Gy), but also depletion of RAD51, which suggested the additional use of imatinib to repress RAD51." (PMID 26784176, 2016). "Following the overexpression or knockdown of circCDYL2 in nasopharyngeal carcinoma cells, RIP experiments revealed that the binding of EIF3D protein to RAD51 mRNA increased or decreased correspondingly." (PMID 38654320, 2024). "Our studies showed that NFBD1 protein is highly expressed in nasopharyngeal carcinoma tissues, and shRNA targeting NFBD1 enhanced the radiosensitivity of CNE1 cells and impaired DNA damage-induced RAD51 foci formation." (PMID 30717758, 2019).
nasopharyngeal carcinoma (continued). "Additionally, we employed cycloheximide (CHX) and MG132 treatments in nasopharyngeal carcinoma cells, and the results indicated that circCDYL2 did not impact the half-life or ubiquitin-mediated degradation of RAD51." (PMID 38654320, 2024). "Moreover, western blotting unveiled that circCDYL2 promoted the expression levels of RAD51 protein in nasopharyngeal carcinoma cells, while it did not influence the expression of BRCA1, RPA1, or Ku70, a key protein within the NHEJ pathway." (PMID 38654320, 2024). "UBC13, HLTF, and SHPRH in the TS pathway, RAD51 and BRCA1 in the HR pathway, and FANCD2 in the FA pathway are highly expressed in cisplatin-resistant nasopharyngeal carcinoma (NPC) cells." (PMID 25051366, 2014). "However, it has also been reported that an increase in the gene expression level of DDR genes may lead to resistance to cisplatin chemotherapy, while the overexpression of BRCA1, BRCA2, RAD51 and RPA1 has been observed in hypopharyngeal and nasopharyngeal carcinoma cells resistant to radiotherapy." (PMID 37740039, 2023). "Previous studies have revealed that CDK6 enhances radioresistance in human malignancies including nasopharyngeal cancer and HPV negative head and neck squamous cell carcinoma possibly by promoting RAD51 and BRCA1 expression and thereby activating homologous recombinational (HR) DNA repair after IR." (PMID 34395263, 2021).
ovarian tumors (9 papers, 2018 to 2025). "In this cohort of breast and ovarian tumors, four rare variants in MSH6, one variant in RAD50, one variant in MRE11A, and two variants in RAD51 have been identified." (PMID 30283497, 2018). "Although PARP inhibitors have been utilized in HR-deficient tumors (e.g., ovarian tumors with BRCA mutations), there is evidence that PTEN plays a role in the HR pathway through upregulation of RAD51, thereby decreasing double-stranded breaks and maintaining genomic stability." (PMID 35954359, 2022). "In both mutant BRCA and wild-type BRCA ovarian tumors, cancer stem cells have been found to be resistant to PARP inhibition and to display increased RAD51 foci formation efficiency after DNA damage." (PMID 35736348, 2022).
squamous cell carcinoma (9 papers, 2005 to 2025). A carcinoma arising from squamous epithelial cells. "Moreover, the positivity of RAD51 was closely related to squamous carcinoma and poor differentiation in NSCLC patients." (PMID 27566579, 2016).
anemia (8 papers, 2015 to 2026). A reduction in the number of red blood cells, the amount of hemoglobin, and/or the volume of packed red blood cells. "Several BRCA1/2 interactors, such as PALB2 (FANCN), RAD51 (FANCR), and BRIP1 (FANCJ), are also Fanconi anemia proteins." (PMID 40841483, 2026). "Mammalian RAD51, in collaboration with BRCA1, BRCA2, and Fanconi anemia proteins, plays a critical role in preventing nascent DNA degradation by MRE11." (PMID 40737093, 2025). "HR is mediated by RAD51, assisted by BRCA1/2, RAD52, RAD54/B, five RAD51 paralogs (XRCC2, XRCC3, RAD51B, RAD51C, and RAD51D), and the Fanconi anemia proteins." (PMID 35155245, 2022). "BRCA1 and 2 interacts with a number of other DNA repair proteins to form a complex system for DNA damage repair, including ATM, RAD51, PALB2, MRE11A, RAD50, NBN, and the Fanconi anemia proteins." (PMID 35785170, 2022). "RAD51 loading and strand invasion are mediated by many factors including BRCA1, BRCA2, five RAD51 paralogs (RAD51B/C/D, XRCC2/3), members of the Fanconi’s anemia (FANC) protein family, RAD54/B, and RAD51AP1 and its paralog NUCKS1." (PMID 34646312, 2021). "Many proteins participate in this protection including BRCA2, RAD51, WRNIP1, or Fanconi anemia proteins (37, 40, 43, –, 45)." (PMID 31757807, 2020). "RAD51C, also known as Fanconi anemia complementation group O (FANCO), is part of the RAD51 gene family and is essential for homologous recombination repair." (PMID 26484312, 2015).
lymph node metastasis (8 papers, 2005 to 2025). "There was a significant association between Rad51 expression and lymph node metastasis with node positive cases numbering 11 (30.6 %) and 31 (58.5 %) in the Rad51 negative and positive groups, respectively (P = 0.0168)." (PMID 24065387, 2014). "And high expression of XRCC3 and RAD51 were associated with large tumor size and axillary lymph node metastasis respectively." (PMID 23977219, 2013). "Elevated RAD51 levels were found in oral cancer, especially in patients with lymph node metastases, and indicated a poor prognosis." (PMID 37894339, 2023). "RAD51 expression was significantly different according to the status of axillary lymph node metastasis (P = 0.004), as well as PR status (P = 0.011) and HER2 status (P = 0.036)." (PMID 23977219, 2013). "Rad51 expression proved to be an independent prognostic factor (P<0.001) as did lymph node metastasis (P=0.009), clinical stage (P=0.004) and tumour grade (P<0.001)." (PMID 15956972, 2005). "Because there was a discrepancy in the association between lymph node metastasis and Rad51 expression in the groups with and without NACRT, we also analyzed Rad51 expression and clinicopathological factors, matching the staging of subjects." (PMID 24065387, 2014). "Lymph node metastasis was more frequently observed in Rad51-positive cases than negative cases (58.5 vs. 30.6 %, P = 0.0168) in patients treated with surgery alone." (PMID 24065387, 2014). "In multivariate analysis, Rad51 was not an independent prognostic factor (P = 0.5287), while lymph node metastasis was an independent prognostic factor (P = 0.0051)." (PMID 24065387, 2014).